DCN (decorin)
Diseases named in the same sentence as DCN in open-access papers (continued):
Sharing a sentence is not in itself a finding about the gene and the disease.
endometriosis (7 papers, 2014 to 2026). The growth of functional endometrial tissue in anatomic sites outside the uterine body. "DCN is associated with pathways relevant to endometriosis pathogenesis and represents a promising biomarker and therapeutic candidate pending future functional and mechanistic validation." (PMID 42139232, 2026). "DCN was significantly upregulated in endometriosis at both transcriptomic and cellular levels, with area under the curve (AUC) > 0.8 in two independent datasets, supporting its diagnostic potential." (PMID 42139232, 2026). "Administration of this drug or progesterone in human endometrial epithelial and stromal cells increased DCN mRNA expression by promoting progesterone binding to the DCN promoters, verified with dienogest-treated endometriosis patients." (PMID 34638928, 2021). "It has been previously shown that induction of DCN by progesterone plays a crucial role in suppressing endometriosis." (PMID 32041647, 2020). "Results show that DCN expression in MGCs from follicles of endometriosis patients exhibit a 5-fold reduction compared to MGCs follicles of control patients (p = 0.008)." (PMID 32041647, 2020). "In summary, we demonstrated that progesterone and dienogest inhibit the proliferation of immortalized human endometriosis epithelial cells and stromal cells via the upregulation of decorin." (PMID 25244916, 2014). "Further examinations will be necessary to determine the optimum strategy for obtaining therapeutic benefits of decorin treatment in patients with endometriosis." (PMID 25244916, 2014). "Also, correlation of DCN expression with progesterone level, endometriosis occurrence, and GC migration potential indicate the novel role of DCN during the preovulatory period and ovulation." (PMID 41465369, 2025). "Taken together, these results indicate that DCN expression in granulosa cells in the ovary might be involved in endometriosis, and further investigation of their role in this disease and the therapeutic role of progesterone may have clinical value." (PMID 32041647, 2020). "A better understanding of DCN’s role in oocyte maturation and its involvement in ovulation and endometriosis may provide treatment for some types of infertility." (PMID 32041647, 2020). "In order to elucidate the role of DCN in endometriosis and to examine whether DCN expression is dysregulated in MGCs and CGCs of women with endometriosis, cells from large preovulatory follicles (> 17 mm) were collected during IVF procedures." (PMID 32041647, 2020). "A better understanding of DCN role in ovulation and endometriosis may provide treatment for some types of infertility." (PMID 32041647, 2020). "Our findings support the hypothesis that DCN plays an important new role during the preovulatory period and ovulation, and stress its involvement in endometriosis infertility." (PMID 32041647, 2020). "However, it is still unclear as to how decorin affects endometrial epithelial cells or endometrial stromal cells as part of its therapeutic effect on endometriosis." (PMID 25244916, 2014). "We also examined DCN mRNA expression in 50 endometriosis patients." (PMID 25244916, 2014). "In conclusion, decorin induced by dienogest appears to play a crucial role in suppressing endometriosis by exerting anti-proliferative effects and inducing cell cycle arrest via the production of p21 human ectopic endometrial cells and eutopic endometrial stromal cells." (PMID 25244916, 2014). "Interestingly, MGCs from women with endometriosis have abnormally low mRNA levels of DCN." (PMID 32041647, 2020). "First, the endometrial stromal cells show a relative deficiency of progesterone-sensitive gene markers associated with endometrial stromal cell decidualization in patients with endometriosis (e.g., IGFBP1, LEFTY2, LUM, DCN, etc.)." (PMID 36104692, 2022).
endometriosis (continued). "In this study, decorin suppressed the expression of MET in endometriotic epithelial cells and endometrial stromal cells, which contributed to its therapeutic effects on endometriosis." (PMID 25244916, 2014). "DCN levels in CGCs were not significantly different in endometriosis patients." (PMID 32041647, 2020). "However, it was not clear whether DCN was involved in the pathology of endometriosis." (PMID 32041647, 2020).
gastric cancer (7 papers, 2015 to 2026). A primary or metastatic malignant neoplasm involving the stomach. "Adding to this, in metastatic gastric cancer, DCN was found to be a marker of desmoplastic cancer associated fibroblasts that drive resistance to immune checkpoint inhibition." (PMID 41392017, 2026). "The analysis of various gastric cancer cell lines and gastric cancer patient samples also revealed a positive association between ELK3 and BMP1, LOXL2, SNAI1, SERPINF1, DCN, and NID1, and these genes were associated with a poor prognosis." (PMID 35409069, 2022). "The gene analysis of samples from patients with gastric cancer indicated that a high ELK3 expression is positively correlated with BMP1, LOXL2, SNAI1, SERPINF1, DCN, and NID1 expression, all of which are closely associated with a poor prognosis." (PMID 35409069, 2022). "In conclusion, the present study is the first to investigate roles of asporin, decorin and their interaction with TGFβ in gastric cancer tissue and corresponding normal tissues." (PMID 34379688, 2021). "Next, we selected PTEN, DCN, and MMP and validated their association with metformin treatment in gastric cancer cells." (PMID 25909163, 2015). "Researchers have widely studied p-mTOR, pS6, p4EBP1, PTEN, MMP7, and DCN expression in human solid cancer tissues, including gastric cancer." (PMID 25909163, 2015). "Notably, the analysis of patients with gastric cancer indicated the marked positive regulation of ELK3 and BMP1, LOXL2, SNAI1, SERPINF1, DCN, and NID1 gene expression, suggesting a significant positive correlation between ELK3 and ECM remodeling-associated genes in gastric cancer." (PMID 35409069, 2022). "Patients with gastric cancer with a high expression of BMP1, LOXL2, SNAI1, SERPINF1, DCN, and NID1 had a poor prognosis." (PMID 35409069, 2022). "First, the correlation between ELK3 expression and BMP1, LOXL2, SNAI1, SERPINF1, DCN, and NID1 expression was analyzed in 19 different gastric cancer cell lines." (PMID 35409069, 2022). "Protein expression levels of pAMPKα, p-mTOR, pS6, p4EBP1, MMP7, DCN and PTEN were analyzed in 39 resected primary gastric cancer samples." (PMID 25909163, 2015). "The ELK3 expression in gastric cancer cells and human gastric cancer samples positively correlated with that of BMP1, LOXL2, SNAI1, SERPINF1, DCN, and NID1, suggesting that this gene signature may be predictive molecular markers for aggressive gastric cancer progression." (PMID 35409069, 2022).
intestinal tumors (7 papers, 2012 to 2025). "Loss of decorin favors intestinal tumor formation in mice, whereas enhancement of decorin production inhibited the proliferation and migration of CRC cells and promoted apoptosis in parallel with upregulated E-cadherin expression." (PMID 32824864, 2020). "Decorin overexpression was furthermore shown to induce apoptosis and cell cycle arrest in rat mesangial cells, and in a decorin knockout mouse model, 30% of mice developed spontaneous intestinal tumours and invasion." (PMID 41300368, 2025). "Our findings of substantially decreased expression in epithelial cells and tumour associated connective tissues are in line with the animal model studies where genetic deletion of DCN facilitates intestinal tumour formation." (PMID 33889206, 2021). "Thirty percent (30%) of decorin knockout mice developed spontaneous intestinal tumors." (PMID 33202923, 2020). "Despite the compensatory effect of BGN (and the potential compensatory role of asporin) in the absence of DCN, 30% of DCN KO mice developed spontaneous intestinal tumors and a high-risk diet enriched in fat amplified and accelerated the tumor development and growth initiated by DCN deficiency." (PMID 26697491, 2015).
invasive breast carcinoma (7 papers, 2006 to 2024). A carcinoma that infiltrates the breast parenchyma. "To identify the factors associated with the expression or secretion of DCN, we compared the levels of stromal and plasma DCN to the histological characteristics in invasive breast cancer, including nuclear atypia, the mitotic count, ER status, and HER2 status." (PMID 34884232, 2021). "Reduced level of decorin expression has been shown to be associated with poorer outcome in invasive breast cancer, and vice versa, high stromal decorin expression has been indicated to predict better prognosis." (PMID 28653173, 2017). "We previously discovered that stromal DCN expression was significantly lower in the tumor-surrounding tissues of patients with invasive breast cancer (IBC) than in those with benign tumors or ductal carcinoma in situ (DCIS)." (PMID 34884232, 2021). "That the stromal-decorin gene set adds prognostic information to proliferation for estrogen receptor-positive women with invasive breast cancer." (PMID 22719844, 2012). "Similarly, transfection of the invasive breast cancer cells (MDA-MB-231) with DCN resulted in the suppression of the carcinogenesis features of these cells." (PMID 38667295, 2024). "Furthermore, the observation that decorin levels are significantly higher in in situ compared to invasive breast carcinomas with MAMCs suggests that up-regulation of decorin prevents tumor spread." (PMID 21791066, 2011). "MT1-MMP expression has been linked to invasive breast cancer and lymph node and distant metastases, which is consistent with the increased gene expression of two MT1-MMP ECM-related substrates, type I collagen, and decorin in Comma/PDK1 cells." (PMID 16551362, 2006).
sarcopenia (7 papers, 2020 to 2025). Progressive decline in muscle mass due to aging which results in decreased functional capacity of muscles. "Importantly, a progressive loss in DCN O-glycanation is also observed in aging, also marked by skin fragility, adipocyte enlargement, and sarcopenia." (PMID 33317052, 2020). "In clinical settings, lower decorin levels have been correlated with reduced muscle mass in patients with liver cirrhosis and were predictive of sarcopenia severity, suggesting its role as a potential biomarker of muscle health." (PMID 41441428, 2025). "In summary, given its multifaceted role in promoting muscle growth, regulating inflammation, and maintaining metabolic function, decorin emerges as a promising molecular target in the prevention and treatment of sarcopenia." (PMID 41441428, 2025). "In the High decorin group, the prevalence of sarcopenia was significantly lower than that in the Low decorin group." (PMID 32231160, 2020). "The comprehensive results show that decorin plays a sarcoprotective role by activating the ITGB1/Akt/mTOR pathway and may serve as a potential therapeutic reagent in age‐associated sarcopenia." (PMID 41350105, 2025). "Nevertheless, the relationships of Myostatin and Decorin with sarcopenia are not clear, as some studies found association between these myokines and sarcopenia, whereas in others the association is unclear or is present in males but not in females." (PMID 36499366, 2022). "However, whether and how decorin is involved in the progress of sarcopenia is unknown." (PMID 41350105, 2025). "Of note, decorin alleviated skeletal muscle fibrosis and atrophy in D‐gal–induced aged mice and NOR‐10 cells by activating the ITGB1/Akt/mTOR signalling pathway, which suggests that decorin supplementation may be a potent therapeutic strategy to combat age‐associated sarcopenia." (PMID 41350105, 2025). "DCN, FSTL1, and COL12A1 are new candidate biomarkers for the comorbidity of SCI and sarcopenia." (PMID 39281413, 2024).
tendinopathy (7 papers, 2013 to 2021). "Regarding extracellular matrix gene expression, collagen III and decorin expression was lower on tendon disease scaffolds." (PMID 34884602, 2021). "However, MMP1, MMP13, MMP10, ADAMTS5, TIMP3, versican, aggrecan, biglycan, decorin, fibronectin, fibrillin and COMP showed an opposite response with strain compared to tendinopathy." (PMID 23830915, 2013). "BGN and TNC were upregulated in tendinopathy, while DCN showed no change." (PMID 35008516, 2021). "While we and others found no tendinopathy-induced changes in DCN mRNA or core protein, post-translational modification of decorin or other proteoglycans, with longer glycosaminoglycans could also contribute to the increase in toluidine blue staining in tendinopathy." (PMID 25837713, 2015).
aneurysm (6 papers, 2012 to 2022). Bulging or ballooning in an area of an artery secondary to arterial wall weakening. "Decorin degradation by GzmB has been shown to contribute to a loss of collagen density in the adventitia of the aorta during abdominal aortic aneurysm, contributing to aneurysm rupture, exsanguination and mortality in mice." (PMID 24205352, 2013). "Decorin within the adventitia has been suggested to protect against aneurysm formation, with decreased levels observed in AAA, whereas when present within macrophages, it is thought to promote aneurysm formation within the abdominal aorta." (PMID 36012466, 2022). "During aneurysm progression, GzmB cleaves many extracellular matrix proteins including DCN and fibrillin-1 both of which play pivotal roles in maintaining vessel wall stability." (PMID 29158532, 2017). "The murine serine protease inhibitor, Serpina3n (SA3N), prevents Granzyme B (GzmB)-mediated DCN degradation and improves collagen remodeling leading to a reduced aneurysm rupture rate and death in a murine model of AAA15." (PMID 29158532, 2017). "In a subsequent study, we demonstrate that adventitial decorin is reduced in apoE-KO aneurysms at sites adjacent to thrombi and in areas of injury." (PMID 22479366, 2012). "Of further interest, elevated GrB and reduced decorin are observed in human aneurysm specimens." (PMID 22479366, 2012). "Because excessive elastolysis mediated by MMP-9 is considered a critical step in aneurysm development, we determined the degree of medial elastin disruption in the CaCl2+PBS and CaCl2+decorin groups." (PMID 25781946, 2015).
cardiac hypertrophy (6 papers, 2016 to 2025). "Decorin has been suggested to induce cardiac hypertrophy by regulating the CaMKII/MEF-2 signaling pathway." (PMID 40843168, 2025). "Furthermore, decorin gene transfer significantly attenuates interstitial fibrosis and cardiac hypertrophy." (PMID 35372585, 2022). "Our results demonstrate that decorin-loaded microrods release decorin for up to a month and can significantly improve cardiac function and attenuate deleterious ventricular dilatation, cardiac fibrosis, and hypertrophy in chronic models of ischemia-reperfusion MI." (PMID 36798333, 2023). "However, the results showed that, despite that the mice clearly exhibited cardiac hypertrophy and fibrosis, the expressions of FN1 and CTGF were not elevated, while the DCN expression was slightly increased in the interstitial region (see Section 3)." (PMID 37766635, 2024). "Therefore, decorin might not be involved in the hypertrophy of atrial myocytes in MR patients, which was mainly related to the Role of NFAT in cardiac hypertrophy pathway." (PMID 27907007, 2016).
COVID-19 (6 papers, 2021 to 2024). A disease caused by infection with severe acute respiratory syndrome coronavirus 2. "This study aims to investigate the predictive potential of serum biomarkers, specifically decorin and biglycan, in assessing the severity and mortality risk among COVID-19 patients." (PMID 39906348, 2024). "A shared spatial expression pattern of DCN was seen in both post-COVID-19 and IPF with elevated staining intensity, corresponding to the increased deposition of extracellular matrices." (PMID 39767799, 2024). "The fundamental goal of this investigation is to determine the level of biglycan and decorin in COVID-19 patients (with moderate and severe symptoms) as compared to the control group." (PMID 39906348, 2024). "DCN was upregulated in the plasma from patients with severe COVID-19, differentiating them from patients with moderate COVID-19." (PMID 39767799, 2024). "decorin levels in the control group were 43.36 ± 1.14 ng/mL, which significantly decreased in patients with moderate COVID-19 (40.24 ± 0.64 ng/mL) and further decreased in severe COVID-19 patients (35.49 ± 1.00 ng/mL), with an ANOVA p value of 0.0059." (PMID 39906348, 2024). "Previously, de Souza Xavier Costa, Ribeiro reported decreased decorin in COVID-19 patients compared to non-COVID-19 patients, as demonstrated by the current study, severe COVID-19 patients exhibit the lowest levels of decorin compared to the control group." (PMID 39906348, 2024). "Serum decorin and biglycan levels are valuable biomarkers for predicting severity and mortality in COVID-19 patients." (PMID 39906348, 2024). "In severe COVID-19 cases, abnormal ECM remodeling has been associated with pulmonary inflammation and fibrosis, suggesting a potential role for decorin and biglycan in these pathological processes." (PMID 39906348, 2024). "Further, a follow-up study of these recruited qRT-PCR-positive COVID-19 patients revealed that serum decorin was significantly higher in survivors (39.6 ± 0.59 ng/mL) compared to non-survivors (35.84 ± 1.61 ng/mL) with a p value of 0.0319." (PMID 39906348, 2024). "Decorin levels significantly decreased from controls (43.36 ± 1.14 ng/mL) to moderate (40.24 ± 0.64 ng/mL) and severe COVID-19 patients (35.49 ± 1.00 ng/mL) (p = 0.0059)." (PMID 39906348, 2024). "Conclusively, our has found that severe COVID-19 patients had significantly lower serum decorin levels and higher biglycan levels compared to healthy controls." (PMID 39906348, 2024). "The levels of decorin and biglycan were measured across three groups: controls, patients with moderate COVID-19, and patients with severe COVID-19, with results expressed as mean ± SEM." (PMID 39906348, 2024). "Elderly COVID-19 cases (> 60 years of age) had higher decorin than the adult COVID-19 cases (p = 0.033)." (PMID 37964271, 2023). "The most striking feature of liver failure was the elevation of CCL23, FGF2, and KRLD1 and depression of KIR3DL1 at admission, while Gal-1 and DCN were decreased later during the history of COVID-19." (PMID 34177897, 2021). "Further, the angiogenic factor PGF, correlated in one study to in-hospital mortality in COVID-19, was, along with CCL19, GAL-9 and DCN, significantly elevated in patients with severe COVID-19 in comparison to healthy controls, as in our IPF ex vivo model and in IPF serum." (PMID 39767799, 2024). "Our study reveals a significant decrease in decorin levels in COVID-19 patients." (PMID 39906348, 2024). "Higher decorin levels correlate with survival in COVID-19 patients." (PMID 39906348, 2024). "Furthermore, decorin can function as an adjunctive treatment when combined with other medicines, offering a reciprocal application in COVID-19 therapy." (PMID 39906348, 2024). "We observed a decrease in the decorin density in COVID-19 lungs." (PMID 37964271, 2023). "The DCN gene responsible for decorin synthesis appeared upregulated in COVID-19 patients." (PMID 37019821, 2023).